LINC00106 (long independently transcribed non-coding RNA 106)
Synonyms: OTTHUMG00000021061; CXYorf8; NCRNA00106
Gene: Long non-coding RNA gene on chromosome X (1,392,679 to 1,400,524, forward strand). Ensembl gene ENSG00000236871.
Diseases named in the same sentence as LINC00106 in open-access papers:
LINC00106 is named in the same sentence as 7 diseases in open-access papers, as found by Europe PMC text mining. Sharing a sentence is not in itself a finding about the gene and the disease. The quoted sentences say what the papers report.
hepatocellular carcinoma (3 papers, 2021 to 2023). A malignant tumor that arises from hepatocytes. "LINC00106 contributes to the carcinogenesis of Hepatocellular carcinoma (HCC)." (PMID 37180577, 2023). "LINC00106 is indicated to promote stemness and metastasis in hepatocellular carcinoma cells." (PMID 35993308, 2022). "Compared to healthy liver tissue, hepatocellular carcinoma (HCC) tissues exhibit upregulation of LINC00106 expression." (PMID 37180577, 2023).
gastric cancer (2 papers, 2020 to 2022). A primary or metastatic malignant neoplasm involving the stomach. "LINC00106 could be regarded as a significant prognostic biomarker in gastric cancer, which was in agreement with the findings of our study." (PMID 35879790, 2022). "The findings from this study indicate that HULC, RP11‐314B1.2, LINC00106, and RP11‐999E24.3 could be considered as potential therapeutic targets or prognostic biomarkers in gastric cancer, and provide a new perspective for cancer pathogenesis research." (PMID 31923354, 2020).
liver cancer (1 paper, 2023). An epithelial or non-epithelial malignant neoplasm that arises from the liver. "METTL3 specifically maintains LINC00106 stability by promoting the differentiation of m6A in liver cancer cells, increasing the abundance of LINC00106 in the nucleus, and promoting the stem cell and metastasis characteristics of liver cancer." (PMID 37180577, 2023).
prostate carcinoma (1 paper, 2023). A carcinoma that arises from epithelial cells of the prostate gland. "It was revealed that high expression of LINC00106 was associated with an unfavorable prognosis among prostate cancer patients." (PMID 37180577, 2023).
thyroid cancer (1 paper, 2022). "Wang and his colleagues found that the expression of LINC00106 in thyroid cancer was significantly lower than that in normal tissues." (PMID 35879790, 2022).
cancer (2 papers, 2020 to 2023). A tumor composed of atypical neoplastic, often pleomorphic cells that invade other tissues. "Moreover, the LINC00106 level of expression significantly varied according to the stage of cancer." (PMID 37180577, 2023).
tumor (1 paper, 2021). "In HCC tissues, we observed a considerably high expression of LINC00106, whose level was positively associated with the tumor differentiation grade of HCC." (PMID 34858996, 2021). "Our findings not only demonstrate the mechanism by which LINC00106 regulates stemness but also offer potential therapeutic targets to deal with tumor metastasis in HCC." (PMID 34858996, 2021). "In addition, the upregulated LINC00106 was positively correlated with tumor diameter (p < 0.05) and TNM stage (p < 0.05)." (PMID 34858996, 2021).